HDAC3 (histone deacetylase 3)
Diseases named in the same sentence as HDAC3 in open-access papers (continued):
Sharing a sentence is not in itself a finding about the gene and the disease.
viral infection (8 papers, 2012 to 2024). "Virus infection increased HDAC3 expression in PK-15 cells, which inversely correlated with KAT8 and mediated PHGDH deacetylation." (PMID 39207107, 2024). "Upon stimulation by pro-inflammatory cytokines, viral infections, or pathogens, IκBα gets phosphorylated and degraded such that p65 and HDAC3 remains free in the cytoplasm, which further translocates into the nucleus." (PMID 31924750, 2020). "So, HDAC1 and HDAC3 can stimulate host antiviral response or inflammatory response, which tend to be depressed by virus infection." (PMID 30261679, 2018). "ATXN3 also directly regulates the ubiquitination state of HDAC3 to modulate IFN-I antiviral activity during viral infection." (PMID 30231063, 2018). "In this study, we demonstrate that virus infection of Namalwa cells induces transient recruitment of HDAC3 (histone deacetylase 3) to IFN-A promoters." (PMID 22685561, 2012). "In the present study, we analyze the patterns of histone H3 acetylation at lysine residues K9 and K14, as well as the recruitment of HAT activities and HDAC3 to IFN-A gene promoters during virus infection." (PMID 22685561, 2012). "Altogether these data indicate that reversal of histone H3K9/K14 acetylation by HDAC3 is required for attenuation of IFN-A gene transcription during viral infection." (PMID 22685561, 2012). "HDAC3-deficient CD8+ cells enhance granzyme B expression and anti-viral effects in a chronic viral infection model, suggesting that HDAC3-targeted inhibition is a potent therapeutic treatment against cancers via enhancement of cytotoxic molecule actions against cancer." (PMID 35163049, 2022). "Therefore, HDAC3 was required for the efficient production of type I IFNs and for the resistance of these mice to viral infection." (PMID 32772249, 2021). "The unexpected decreased expression levels of both HDAC1 and HDAC3 may undermine the finding that virus infection decreased the acetylation of histone H3." (PMID 30261679, 2018). "Because virus infection stimulated HDAC3 expression, we tested whether HDAC3 was recruited to IFN-A gene promoters during virus infection." (PMID 22685561, 2012). "In Western blots, in addition to the 50-kDa form of HDAC3, we detected a slower migrating complex reacting with HDAC3 antibodies that might correspond to a post-translationally modified form of HDAC3 that appears during virus infection." (PMID 22685561, 2012). "Besides, potential HDAC3 deacetylation targets also involved few RNA-binding proteins, including for example ZC3H7B, which plays a role during virus infection." (PMID 35994477, 2022). "Ordered recruitment of GCN5 and HDAC3 activities to these promoters, starting at 6 h and 12 h, respectively, clearly indicated that the IFN-A gene transcription was coordinately regulated during virus infection." (PMID 22685561, 2012). "However, it seems that downregulation of both HDAC1 and HDAC3 by virus infection was not correlated with the decreased levels of histone H3 acetylation, which emphasized the complexity of the mechanisms for the regulation of histone acetylation following virus infection." (PMID 30261679, 2018).
diffuse large B-cell lymphoma (7 papers, 2015 to 2025). "Overexpression of HDAC3 in diffuse large B-cell lymphoma (DLBCL) interferences with STAT3 and causes increased expression of it." (PMID 26865932, 2015). "In a cellular model of diffuse large B-cell lymphoma (DLBCL), the inhibition of HDAC3 rescues the aberrant epigenetic programming associated with CREBBP mutations, enhancing BCL6-mediated antigen presentation and the release of IFN-γ." (PMID 40006729, 2025). "This hypothesis aligns well with recent findings highlighting the importance of effectively targeting HDAC3 to overcome resistance to pan-HDAC inhibitors in diffuse large B-cell lymphoma." (PMID 40284412, 2025). "HDAC3 knockdown inhibits STAT3 (Tyr705) phosphorylation and survival of pSTAT3-positive DLBCL (Diffuse large B cell lymphoma cells)." (PMID 28968979, 2017).
infertile (7 papers, 2022 to 2025). "Loss of HDAC3 activity in the mouse model resulted in a decidualization defect and infertility due to implantation failure." (PMID 35409163, 2022).
ischemia (7 papers, 2015 to 2025). A hypoperfusion of the BLOOD through an organ or tissue caused by a PATHOLOGIC CONSTRICTION or obstruction of its BLOOD VESSELS, or an absence of BLOOD CIRCULATION. "After one month of tamoxifen injection, we used transient focal cerebral ischemia (tFCI) to induce a comparable decrease of cerebral blood flow in HDAC3-miKO mice and WT mice during the ischemia stage, as detected by laser Doppler flowmetry." (PMID 39744685, 2025). "In ischemia, specific HDAC isoforms (e.g., HDAC1, HDAC2, HDAC3, and HDAC6) have been implicated in microglial activation, glial reactivity, and disruption of immune balance." (PMID 40867911, 2025). "In this study, we explored the role of myeloid HDAC3 in ischemia-induced retinal neurovascular injury by subjecting myeloid-specific HDAC3 knockout (M-HDAC3 KO) and floxed control mice to retinal IR." (PMID 38997746, 2024). "Based on this, efficient and specific pharmacological inhibition of HDAC3 in vivo and knock-down of HDAC3 in vitro in models of ischemia were performed." (PMID 27965534, 2016). "For instance, HDAC3 has been shown to suppress Nrf2 activity in various models of ischemia." (PMID 40867911, 2025). "The present study provides evidence that HDAC3 inhibition may have a role in PC the brain against ischemia." (PMID 27965534, 2016). "In ischemia-reperfused mice, lncRNASNHG3 inhibits microglia activation and secretion of pro-inflammatory factors (TNF-α and IL-6) by decreasing histone deacetylase 3 (HDAC3) expression." (PMID 35860297, 2022).
metabolic syndrome (7 papers, 2012 to 2023). A cluster of metabolic risk factors for CARDIOVASCULAR DISEASES and TYPE 2 DIABETES MELLITUS. "Indeed, a recent report indicated that liver deletion of Hdac-3 causes a metabolic syndrome and increases enzymes involved in cholesterol and lipid synthesis." (PMID 23468869, 2013). "High expression of HDAC3 in the liver has been shown to contribute to high-fat diet-induced metabolic syndrome by suppressing the PPAR-γ and LXR-α-pathways in rats." (PMID 27904654, 2016). "HDAC3 is involved in hepatic gluconeogenesis, a process that is dysregulated in metabolic syndrome induced by high fat diet." (PMID 23363995, 2012). "Fructose feeding was shown to be associated with increased levels of histone deacetylases 3 (HDAC3), thus suggesting that HDAC3 represents a crucial component in the network linking fructose to neuroinflammation in metabolic syndrome, through the activation of TLR4/NF-kB pathway." (PMID 33374894, 2020).
neuroblastoma (7 papers, 2008 to 2022). Neuroblastoma (NB) is the most common solid, extracranial childhood tumor. "Omega-3 fatty acids delay cognitive decline in the elderly if taken before the onset of AD symptoms; docosahexaenoic acid decreases HDAC3 levels in neuroblastoma cells." (PMID 36432638, 2022). "We showed that HDAC2 cooperates with MYCN to suppress apoptosis mediated by miR-183, and that HDAC3 interacts with MYCN to transcriptionally repress the GRHL1 transcription factor, which exerts tumor suppressive effects in neuroblastoma." (PMID 27572323, 2016). "In the neuroblastoma cell line ND-7, thesame group shows that the degree of PPARγ activation induced by PGJ2 ismodulated through an interaction with retinoblastoma protein (Rb) and the classI histone deacetylase 3 (HDAC3)." (PMID 18725982, 2008).
non-small cell lung carcinoma (7 papers, 2017 to 2025). A group of at least three distinct histological types of lung cancer, including non-small cell squamous cell carcinoma, adenocarcinoma, and large cell carcinoma. "HDAC3 also plays a crucial role in the development of non-small cell lung cancer (NSCLC) driven by the KL and KP genotypes." (PMID 39620228, 2024). "A recent report showed that HDAC3 was required for non-small cell lung cancer cell tumorigenic growth, while central to the repression of p65 RelA/NF-κB-mediated induction of SASP in these cells." (PMID 34503224, 2021). "Moreover, HDAC3 inhibition facilitated non-small cell lung cancer in overcoming osimertinib resistance." (PMID 32404892, 2020). "For example, HDAC3 has been shown to promote expression of the lung cancer lineage transcription factor NKX2-1, which drives progression and therapeutic resistance in non-small-cell lung cancer (NSCLC)." (PMID 41444923, 2025).
osteosarcoma (7 papers, 2019 to 2024). A usually aggressive malignant bone-forming mesenchymal neoplasm, predominantly affecting adolescents and young adults. "We have demonstrated that 4SC-202 inhibits osteosarcoma cell growth in vitro and in vivo, and advanced our understanding of the key roles of HDAC1, HDAC2, and HDAC3 in the biological behaviors of osteosarcoma." (PMID 34439353, 2021). "In addition, the expression levels of several other HDAC family members, such as HDAC2, HDAC3, HDAC5, and HDAC8 were also upregulated, suggesting a potentially redundant function of HDACs in osteosarcoma." (PMID 37457661, 2023).
type 1 diabetes (7 papers, 2017 to 2024). "It has been reported that HDAC3 inhibition regulates Keap1/Nrf2 in tumor cell lines or type 1 diabetes-associated aortic pathologies, which is through modulating the expression of miR-200a that binds to the 3′-terminal region of the Keap1 mRNA to inhibit its translation." (PMID 31101061, 2019). "In streptozotocin-induced type 1 diabetic mice, HDAC3 inhibition exerted a hypoglycemic effect and improved the morphology of islets and the function of β-cells." (PMID 34301918, 2021).
asthma (6 papers, 2018 to 2023). "Further studies are needed to assess the role of HDAC3 in the functionality of individual AM subpopulations in the pathogenesis of lung diseases, such as asthma and cancer." (PMID 32732898, 2020). "Future investigations should investigate whether the effects of either HDAC3 inhibition or knock-out in macrophages translates to a beneficial effect on inflammation in asthma or COPD." (PMID 34968229, 2019). "Whether selective pharmacological inhibition of HDAC3 in in vivo models of asthma or COPD will be beneficial remains to be seen." (PMID 34968229, 2019). "We had also shown that HDAC3 was a key epigenetic regulator of IL-33 in animal models of asthma." (PMID 30562364, 2018). "HDAC3 inhibitors have been proposed as therapeutic targets to combat inflammation in COPD and asthma, since HDAC3 is a positive regulator of NF-κB mediated inflammation." (PMID 37373058, 2023). "With respect to the inflammatory lung diseases asthma and COPD, HDAC3 is reportedly an important regulator of inflammation." (PMID 29498635, 2018). "Given that HDAC3 is a positive regulator of NF-κB mediated inflammation, inhibitors of HDAC3 have been proposed as novel therapeutics to combat inflammation in COPD and asthma." (PMID 34968229, 2019).
inflammatory bowel disease (6 papers, 2018 to 2025). A spectrum of small and large bowel inflammatory diseases of unknown etiology. "Specifically, an intestinal epithelial cell specific HDAC3 knockout mouse line was bred (HDAC3ΔIEC) to investigate inflammatory bowel disease (IBD) progression." (PMID 33221945, 2021). "Periphery CD4 T cells of HDAC3 knockout mice were skewed toward RORgammat(+) IL-17-producing Th17 cells, leading to inflammatory bowel disease." (PMID 30402512, 2018). "The RORα/HDAC3-mediated attenuation of NF-κB signaling controls the balance of inflammatory responses, suggesting that therapeutic strategies targeting this epigenetic regulation may be beneficial in the treatment of chronic inflammatory diseases, including inflammatory bowel disease (IBD)." (PMID 34973135, 2023).
memory impairment (6 papers, 2017 to 2025). "A site within the intron of NCOR2, which regulates gene expression by activating histone deacetylase 3, and whose loss is associated with memory impairment, also showed nominally significant differential hydroxymethylation (p = 1.1 × 10−4)." (PMID 37139321, 2023). "We show that melatonin attenuates CRSD‐induced hippocampal‐dependent spatial learning and memory impairment and reverses the alterations of HDAC3 and circadian rhythms in rats." (PMID 37721401, 2024). "It was reported that HDAC3 inhibitors increased histone H3 and H4 acetylation and relieved memory impairment." (PMID 36902234, 2023). "We found that SCEP significantly improved the cognitive and memory impairment of the AD mouse model and reduced AD pathology by suppressing HDAC3, in turn increasing the expression of BDNF and NT3 via gut microbiota and SCFAs, suggesting that SCEP can slow down the progression of AD." (PMID 40732937, 2025). "These are the genes that fail to normally express in the old brain after OLM training but are rescued by HDAC3 deletion and may therefore function as a mechanism through which HDAC3 deletion ameliorates age-related memory impairments." (PMID 30127461, 2018). "In the current study, we identified that pretreatment with melatonin significantly attenuated CRSD‐induced intermediate‐term and long‐term spatial learning and memory impairment, and this protective effect may attribute to the regulation of HDAC3 and Bmal1/Clock complex." (PMID 37721401, 2024).
allergic disease (5 papers, 2018 to 2024). An immune response that occurs following re-exposure to an innocuous antigen, and that requires the presence of existing antibodies against that antigen. "HDAC3-specific inhibitors would be useful for the treatment of allergies, PCA, PSA and food-induced systemic anaphylaxis." (PMID 31597362, 2019). "Peptides corresponding to the domain of HDAC3 necessary for an interaction of HDAC3 with FcεRI can be developed as drugs targeting allergies and anaphylaxis." (PMID 31597362, 2019). "More recently, HDAC3 has been shown to be necessary to activate IL-4 and loss of HDAC’s limits IL-4 mediated allergic disease." (PMID 30562364, 2018). "Thus, epigenetic modulation of PC differentiation towards a more regulatory phenotype by BA or targeted inhibition of HDAC3 might be a potential therapeutic target in autoimmune and allergic diseases." (PMID 35333906, 2022). "miR-21a mimic exerted a negative effect on the increased expression of NUR77 and the hallmarks of allergic reactions, such as COX2, HDAC3, and MCP1, in PCA." (PMID 38666929, 2024).
chronic kidney disease (5 papers, 2022 to 2025). Impairment of the renal function secondary to chronic kidney damage persisting for three or more months. "The regulation of chronic kidney disease (CKD) by HDAC3 appears to involve the peroxisome PPARγ/Klotho pathway." (PMID 39143689, 2025). "For example, in chronic kidney disease, there is a positive correlation between HDAC3 expression and fibrosis, and HDAC3 inhibition has been effective in reducing disease progression." (PMID 39595579, 2024). "Importantly, preclinical studies in chronic kidney disease models demonstrate that HDAC3 overexpression promotes macrophage pro-inflammatory polarization through Lys-122 deacetylation of the NF-κB p65 subunit." (PMID 40867535, 2025).
esophageal cancer (5 papers, 2015 to 2025). A primary or metastatic malignant neoplasm involving the esophagus. "The expression levels of HDAC1, HDAC2 and HDAC3 were significantly up-regulated in esophageal cancer specimens compared to normal specimens." (PMID 37171386, 2023). "To determine the expression of the complex-forming partners, SOX4, EZH2 and HDAC3, in esophageal cancer cell lines and tissues, we used qRT-PCR." (PMID 25644061, 2015). "Our study showed that both tumor-specific histone methylation and higher expression levels of histone deacetylases HDAC1, HDAC2 and HDAC3 are involved in miR-497 downregulation in esophageal cancer cells, suggesting the epigenetic complexity of miRNA deregulation." (PMID 37171386, 2023). "We show that miR-31 is repressed in invasive esophageal cancers cell lines and that miR-31 levels inversely correlate with SOX4, EZH2 and HDAC3 expression." (PMID 25644061, 2015).
lung adenocarcinoma (5 papers, 2011 to 2023). A carcinoma that arises from the lung and is characterized by the presence of malignant glandular epithelial cells. "Considering that overexpression of the epigenetic modifiers HDAC1 and HDAC3 is associated with a poor prognosis in lung adenocarcinoma, Vorinostat looks to be a promising therapeutic option." (PMID 37710391, 2023). "Lastly, quantification of HDAC-3 mRNA in tissue specimens of 94 lung adenocarcinoma patients revealed its correlation with clinicopathologic parameters, suggesting a significantly poorer prognosis in patients overexpressing HDAC-3 isoform." (PMID 34441281, 2021). "Hdac3 has been shown to be upregulated in adenocarcinoma of the lung, which was related to its poor prognosis." (PMID 33143661, 2020). "Additionally, we identified HDAC3 as a potential oncogene in lung adenocarcinoma (LUAD)." (PMID 37553641, 2023).
lymph node metastasis (5 papers, 2016 to 2023). "Increased nuclear HDAC3 correlates with lymph node metastasis (P < 0.001) and advanced clinical stage (P < 0.001), but increased cytoplasmic HDAC3 does not (P > 0.05)." (PMID 26918727, 2016). "However, a significant positive correlation was noted between HDAC3 expression and tumor node metastasis staging, lymph node metastasis (LNM) and tumor size." (PMID 35578338, 2022). "Most importantly, patients with high co-expression of nuclear HDAC3 and cytoplasmic CDH1 had shorter survival times (P < 0.001), more frequent lymph node metastasis (P < 0.001), and advanced clinical stage (P < 0.001)." (PMID 26918727, 2016). "Nuclear HDAC3 staining correlated with lymph node metastasis (P < 0.001) and clinical stage (P < 0.001), but did not correlate with patient's gender, age, tumor location, tumor size, tumor differentiation, invasion depth, distant metastasis, abdominal pain, jaundice, or nervous invasion (P > 0.05)." (PMID 26918727, 2016).